LITAFD (LITAF domain containing)
Gene: Protein-coding gene on chromosome 16 (8,875,704 to 8,885,353, forward strand). Ensembl gene ENSG00000283516.
Subcellular location: Membrane
Gene Ontology:
Molecular function: zinc ion binding
Biological process: regulation of cytokine production
Cellular component: cytoplasmic side of late endosome membrane; cytoplasmic side of lysosomal membrane; nucleus; membrane
Homologues: Orthologues: chimpanzee LITAFD (96% identical), macaque LITAFD (90% identical), dog LITAFD (72% identical), guinea pig LITAFD (72% identical), mouse Litafd (69% identical), rat Litafd (68% identical), rabbit LITAFD (65% identical).
Diseases named in the same sentence as LITAFD in open-access papers:
LITAFD is named in the same sentence as 4 diseases in open-access papers, as found by Europe PMC text mining. Sharing a sentence is not in itself a finding about the gene and the disease. The quoted sentences say what the papers report.
melanoma (1 paper, 2021). A malignant, usually aggressive tumor composed of atypical, neoplastic melanocytes. "The antagonistic pathogenesis of vitiligo in relation to cancer specific enhanced cell motility and/or metastasis on typical melanoma predilection sites underlines a plausible involvement of RCBTB1, LITAFD, NUBPL, and PTP4A1." (PMID 34696794, 2021).
vitiligo (1 paper, 2021). Generalized well circumscribed patches of leukoderma that are generally distributed over symmetric body locations and is due to autoimmune destruction of melanocytes. "In total, we propose the genes NUBPL, PHF11, SETDB2, RCBTB1, PTP4A1, and at a weaker replication level the genes LITAFD, CARHSP1 and OR2C1 as possible candidates for vitiligo-like depigmentation in grey horses." (PMID 34696794, 2021).
tumor (1 paper, 2021). "The highlighted genes PHF11, SETDB2, CARHSP1 and LITAFD, are associated with the innate immune system, while the genes RCBTB1, LITAFD, NUBPL, PTP4A1, play a role in tumor suppression and metastasis." (PMID 34696794, 2021).
LITAFD also shares sentences with these, for which no sentence is quoted: cancer (1 paper).